TIGIT (T cell immunoreceptor with Ig and ITIM domains)
Diseases named in the same sentence as TIGIT in open-access papers (continued):
Sharing a sentence is not in itself a finding about the gene and the disease.
glioma (continued). "In our study, Siglec15 was broadly and positively correlated with immune checkpoints that have been reported as potential biomarkers of glioma, such as PD1, PDL1, PDL2, Lag3, CTLA4, TIGIT, CD276 (B7-H3), IDO1 and CD47." (PMID 37325664, 2023). "We further analyzed the expression distribution of immune checkpoints gene (including CD274, CTLA4, HAVCR2, LAG3, PDCD1, PDCD1LG2, TIGIT, and SIGLEC15) in glioma tissues and normal brain tissues using the TCGA database." (PMID 36915038, 2023). "In early phase I clinical trials in patients with recurrent glioma (NCT04656535) and in patients with advanced solid tumors (NCT03628677), the safety and efficacy of co-blocking TIGIT and PD-1 using the mAbs AB154 and AB122 are being evaluated." (PMID 34298735, 2021). "At last, VISTA mRNA expression levels appeared to be the highest in all glioma cases (low and high grade) when compared to those of other critical immune checkpoints, Tim-3, PD-1, CTLA-4, LAG-3 and TIGIT (p < 0.0001)." (PMID 34728682, 2021). "The expression of TIGIT and PD1 by Treg cells was shown to enhances their immunosuppressive functions and contribute to tumor progression both in glioma murine models and GBM patients." (PMID 34025646, 2021). "In newly diagnosed grade 3 gliomas, the descending frequency of expression was A2aR > PD-1 > CD39 > CD73 > TIGIT > LAG-3 > BLTA > CD160 > CTLA-4 > KIR > TIM3 on CD8+ T cells." (PMID 32721947, 2020). "In addition, immunosuppressive molecules such as PD-L1, TIGIT and CD80, which are expressed at increased levels on glioma cells, also negatively regulate the interaction between antigen-presenting cells and T cells." (PMID 36845098, 2023). "Contrary to the high expression of TIGIT in TILs isolated from glioma patients, T cells isolated from MS lesions showed no expression of TIGIT." (PMID 34298735, 2021). "Anti-PD-1 therapy was also efficient in prolonging the survival of GL261 glioma-bearing mice, particularly when combined with anti-T cell immunoglobulin and ITIM domain (TIGIT) therapy, where TIGIT is an immune checkpoint receptor that plays a critical role in cancer immunity." (PMID 34944776, 2021). "By conducting Pearson correlation analysis on glioma samples from the CGGA and TCGA databases, it was discovered that the expression of SOCS1 is significantly positively correlated with several known inhibitory immune checkpoints, including HVEM, TIM-3, PD-1, PDCD2, TIGIT, CD200R1, CTLA4, and CD47." (PMID 39654174, 2024). "Furthermore, CD96 shows strong concordance with other immune checkpoint proteins such as TIGIT, CD226, and CRTAM, as well as established markers including PD-L1, CTLA-4, TIM-3, and STAT3, suggesting its potential for synergistic antitumoral effects in glioma immunotherapy​​." (PMID 38342925, 2024). "We found that in patients with glioma, B7‐H3, LAG3 and TIM3 were significantly raised, while the expression of PD‐L1, BTLA, TIGIT, PD‐1 and CTLA4 did not seem to be significantly different from those of normal individuals." (PMID 35668574, 2023).
non-small cell lung carcinoma (32 papers, 2015 to 2025). A group of at least three distinct histological types of lung cancer, including non-small cell squamous cell carcinoma, adenocarcinoma, and large cell carcinoma. "Published data from clinical trials with anti-TIGIT monoclonal antibodies or bispecific antibodies in non-small-cell lung cancer." (PMID 40075753, 2025). "Non-small-cell lung cancer is a subtype of cancer in which TIGIT overexpression has been demonstrated." (PMID 40362333, 2025). "In the study, treatment of patients with non-small-cell lung cancer with Rocaltrol (active vitamin D3) decreased the expression of PD-1, TIM-3, and TIGIT and resulted in cytokine production associated with anti-tumor immunity." (PMID 38891058, 2024). "This agent, which targets TIGIT, shows marked efficacy in the treatment of metastatic non-small cell lung cancer (NSCLC), especially when paired with anti-PD-L1 therapies." (PMID 38106415, 2023). "The anti-TIGIT mAb tiragolumab has progressed the furthest in clinical trials for the treatment of non-small cell lung carcinoma (NSCLC)." (PMID 37109579, 2023). "Recently, there has been noticeable progress in combining anti-PD-1/anti-CTLA-4 and anti-PD-L1/anti-TIGIT, which have an objective response rate of 30-50% in advanced non-small-cell lung cancer (NSCLC)." (PMID 35197968, 2022). "In a first-line therapy for non-small cell lung cancer, atezolizumab plus tiragolumab (an anti-TIGIT antibody) showed superior clinical efficacy as compared with anti-PD-L1 therapy alone recently." (PMID 33717059, 2021). "Recently, anti-TIGIT mAb (tiragolumab) has demonstrated promising clinical efficacy in non-small cell lung cancer treatment when combined with an anti-PD-L1 drug (Tecentriq), leading to phase III trial initiation." (PMID 33670993, 2021). "Most notably, the phase II CITYSCAPE trial on locally advanced or metastatic non-small cell lung cancer demonstrated a nearly doubled overall response rate of combined anti-TIGIT/-PD-1 therapy compared to anti-PD-1 therapy alone." (PMID 33918309, 2021). "The effects of TIGIT blockade in non-small-cell lung cancer in combination with anti-PD-L1 mAbs (NCT04294810; NCT04256421) and in advanced metastatic solid tumors in combination with anti-PD-1 mAbs (NCT03119428; NCT04047862) are being analyzed." (PMID 32764229, 2020). "Additionally, ongoing clinical trials of anti-TIGIT antibodies in non-small-cell lung cancer (phase II CITYSCAPE trial) have shown encouraging treatment outcomes." (PMID 37383234, 2023). "According to the phase I and II trials, the TIGIT inhibitor tiragolumab alone or in combination with the PD-L1 inhibitor atezolizumab, has achieved statistically significant results in the treatment of multiple solid malignancies, most notably non-small cell-lung cancer." (PMID 35320940, 2022). "In addition, several ongoing clinical trials targeting TIGIT as the treatment of advanced solid cancers including non-small-cell lung cancer (such as NCT03119428, NCT02913313, NCT03563716, and NCT02794571), either as a single agent or in combination with other ICIs, are being performed." (PMID 35320940, 2022). "In a clinical trial, combining the anti-TIGIT (T cell immunoreceptor with Ig and ITIM domains) Mab (monoclonal antibody) tiragolumab with atezolizumab improved outcomes in non-small cell lung cancer." (PMID 37946136, 2023). "Unfortunately, the NCCN guidelines for the treatment of non-small-cell lung cancer from January 2025 do not indicate the place of drugs using the blockade of the TIGIT, TIM-3, or LAG-3 checkpoints." (PMID 40362333, 2025). "TIGIT inhibitors, such as tibolumab, vibostolimab, ocperlimab, M-6223, ASP-8374, COM-902 and IBI-939, have been under clinical trials in patients with non-small cell lung cancer (NSCLC), esophageal squamous cell carcinoma (ESCC) and gastric adenocarcinoma (GAC)." (PMID 36211383, 2022).
non-small cell lung carcinoma (continued). "The upregulation of checkpoint inhibitors LAG-3, TIM-3, TIGIT, and VISTA on T cells post anti-PD-L1 ICB has been described in many tumors, including melanoma and non-small cell lung carcinoma (NSCLC), as a mechanism for acquired resistance." (PMID 34322780, 2021).
autoimmune disease (31 papers, 2013 to 2026). A disorder resulting from loss of function or tissue destruction of an organ or multiple organs, arising from humoral or cellular immune responses of the individual to their own tissue constituents. "A diminished proportion of TIGIT+ Tregs is recognized as a hallmark of autoimmune disease pathogenesis." (PMID 41465029, 2025). "Given the association of TEX with better response to therapy in autoimmune disease, we explored the relationship between TIGIT+KLRG1+ TEX frequency and HLA risk alleles in the setting of immune interventions leveraging recent clinical trials." (PMID 38650930, 2024). "In autoimmune diseases, the association between TIGIT-expressing cells and pathogenesis and the function of human-TIGIT (hu-TIGIT) signalling modification have not been fully elucidated." (PMID 37161050, 2023). "A decrease in TIGIT + CD4 + T cells was associated with severe forms of autoimmune diseases such as multiple sclerosis, atopic dermatitis, ulcerative colitis, and systemic lupus." (PMID 35821240, 2022). "Previous studies in mouse model found that loss of TIGIT or blocking TIGIT signaling pathway led to the hyperproliferative T cells responses, aggravation of the inflammation, and promoted susceptibility to autoimmune diseases." (PMID 35720417, 2022). "The TIGIT/CD226 pathway has been linked genetically to several autoimmune diseases, including MS, RA, and T1D." (PMID 34298735, 2021). "Genome-wide association studies have linked allelic variants in the TIGIT/CD226 pathway to several autoimmune diseases such as type 1 diabetes, rheumatoid arthritis, and multiple sclerosis." (PMID 33413573, 2021). "Genome-wide association studies have linked TIGIT to multiple human autoimmune diseases including type 1 diabetes, multiple sclerosis, and rheumatoid arthritis." (PMID 28545567, 2017). "A study underscored the significance of TIGIT, a coinhibitory receptor, in modulating Th1 Tregs—a subgroup of Tregs characterized by diminished suppressor activity and increased proinflammatory cytokine production, often linked to autoimmune disorders." (PMID 40567374, 2025). "However, the loss of TIGIT led to exacerbated autoimmune disease after immunization, or when TIGIT-deficient mice were crossed to an appropriate auto-reactive T-cell mouse line." (PMID 31974523, 2020). "Similarly, the frequencies of TIGIT-expressing immune cells have been reported to be associated with the disease activities of autoimmune diseases." (PMID 32793241, 2020). "The TIGIT/CD226 pathway has been associated with several human autoimmune diseases and studies in mice demonstrate that interference in this pathway may be an attractive approach to modulate autoimmune diseases." (PMID 24376654, 2013). "Intriguingly, TIGIT expression levels show wide variation among individuals, which might explain one of the relevant mechanisms of the phenotypic and functional heterogeneity of NK cells and might be associated with susceptibility to autoimmune diseases." (PMID 35720417, 2022). "Interestingly, genome-wide association studies have linked a polymorphism in CD226 to multiple human autoimmune diseases including MS and T1D, suggesting that the TIGIT:CD226 pathway may also play a role in human autoimmunity." (PMID 31974523, 2020). "Subsequently, we investigated whether agonistic anti-TIGIT treatment can be beneficial for the development of atherosclerosis since TIGIT-mediated dampening of T cell responses has been associated with decreased susceptibility to several autoimmune diseases." (PMID 24376654, 2013). "TIGIT has been recognized as a negative regulator of T cell function, which participates in the pathogenesis of autoimmune diseases, malignancies, and chronic viral and parasitic infections." (PMID 40526725, 2025). "The outcomes designate TIGIT as a vital regulator of Treg stability and a potential therapeutic target for cancer and autoimmune diseases." (PMID 40567374, 2025).
autoimmune disease (continued). "As a therapeutic target, inhibition of the TIGIT pathway induces a variety of autoimmune diseases, while TIGIT function augmentation ameliorates autoimmune settings in mice." (PMID 38474367, 2024). "Our comprehensive analysis of autoimmune diseases proved that some subsets of TIGIT+ CD4+ T cells, especially TIGIT+ Tfh and Tph cells, were associated with disease activity." (PMID 37161050, 2023). "Our findings indicate that anti-hu-TIGIT agonistic mAb can manipulate T cell imbalance, and it has a potential clinical application as therapeutic agents for autoimmune diseases." (PMID 37161050, 2023). "Next, to clarify TIGIT and PD-1 expression of each Treg cell in autoimmune diseases, we compared them with the patients with active RA and the HCs." (PMID 37161050, 2023). "This work is focused on the characteristics of TIGIT and its roles in the regulation of autoimmune responses with the aim to provide novel therapeutic strategies in the treatment of autoimmune diseases." (PMID 35720417, 2022). "We then discuss recent approaches and future directions to leverage our knowledge of TIGIT as therapeutic target in autoimmune diseases." (PMID 35720417, 2022). "Regulatory B cells (Bregs) were shown to mitigate autoimmune diseases via immunosuppressive cytokines and immunoregulatory pathways including TIGIT." (PMID 35720417, 2022). "Blockade of TIGIT pathway exacerbates multiple autoimmune diseases, whereas enhancement of TIGIT function has been shown to alleviate autoimmune settings in mice." (PMID 35720417, 2022). "As the CD226–TIGIT axis is centrally involved in the Th1/Th17 balance in cancer and autoimmunity, possible side effects of TIGIT blockade include exacerbation of autoimmune diseases similar to combined PD-1/CTLA-4 blockade." (PMID 35410311, 2022). "Different strategies such as TIGIT overexpression, agonistic anti-TIGIT mAb, recombinant CD155 protein, and TIGIT-Ig fusion protein have been used in mice models for treatment of autoimmune diseases." (PMID 35720417, 2022). "The Abs presented above can serve as potential tools for evaluate TIGIT function in autoimmune diseases and provide novel therapeutic strategies by modulating TIGIT pathway." (PMID 35720417, 2022). "Over the past few years, TIGIT has emerged as an important coinhibitory receptor and has been extensively studied in cancer, chronic infection, and autoimmune diseases." (PMID 34100383, 2021). "The autoimmune disease studies published to date have mainly focused on one single receptor, i.e., either TIGIT or CD226." (PMID 32793241, 2020). "On the other hand, TIGIT competes for CD155 binding with CD226, a receptor associated with the hyperinflammation of autoimmune disorders, suggesting the existence of a host-driven “cytokine storms” axis opposed to the virally induced immune suppressant, TIGIT." (PMID 32655579, 2020). "Previous genome-wide association studies also revealed an important link between the CD226/TIGIT immune checkpoint and autoimmune diseases; however, its relationship with the pathogenesis of PBC has not been illustrated." (PMID 32793241, 2020). "The main difference between our study and previous studies investigating TIGIT or CD226 in autoimmune diseases is that we simultaneously explored the T cells expired molecular, TIGIT, as well as its competitive receptor, CD226." (PMID 32793241, 2020). "In autoimmune diseases, TIGIT has a protective role in rheumatoid arthritis, multiple sclerosis, and type 1 diabetes; however, TIGIT expression levels are substantially reduced in these diseases." (PMID 30364127, 2018). "Additionally, agonistic antibodies against TIGIT have been shown to alleviate the severity of autoimmune diseases." (PMID 41597269, 2026). "We hypothesized that inhibitory signals against TIGIT-expressing cells, which are increased in autoimmune diseases, would be useful for treating these diseases." (PMID 37161050, 2023).
autoimmune disease (continued). "Next, to explore whether these differences in inhibitory receptor-expressing T cell subsets were related to autoimmune disease activities, we analysed the correlations between the proportions of TIGIT- and PD-1-expressing cells and disease activity indexes." (PMID 37161050, 2023). "Our mAb acts on cells with elevated TIGIT expression, and this mechanism shows that the mAb can directly suppress the activation of autoreactive T cells in autoimmune diseases, even if the self-antigen is unknown." (PMID 37161050, 2023). "Increasing data for the roles of TIGIT in autoimmunity suggest that enforcement of TIGIT signaling and its downstream consequences might prevent or treat autoimmune diseases." (PMID 35720417, 2022). "On the contrary, TIGIT inhibition is associated with an altered cytokine expression profile, which may pave the way to an IFN-γ driven Th1/Th17 shift predisposing to autoimmune diseases or inflammatory conditions like psoriasis." (PMID 35410311, 2022). "Expression profile and potential roles of TIGIT in autoimmune diseases." (PMID 35720417, 2022). "The scope of this review is to outline the characteristics of TIGIT, summarize its roles in multiple autoimmune diseases, and discuss the therapeutic potential and mechanism of TIGIT to regulate immune responses and to ameliorate disease activity in autoimmune disorders." (PMID 35720417, 2022). "TIGIT is recognised for its protective role in autoimmune diseases as well as cancer." (PMID 33995362, 2021). "The immune regulatory function of co-inhibitory receptors, including CTLA-4, PD-1, TIM-3, TIGIT, and LAG-3, was first discovered in the setting of autoimmune disease models, in which their blockade or deficiency resulted in induction or exacerbation of the disease." (PMID 31974523, 2020). "In addition to its protective role in autoimmune diseases, TIGIT was also explored in cancer and chronic viral infections." (PMID 28545567, 2017). "Therefore, targeting TIGIT/CD226 axis might be a more efficient manipulation of T cells in autoimmune diseases." (PMID 35720417, 2022). "Therefore, TIGIT enforcement is an attractive therapeutic to ameliorate autoimmune diseases." (PMID 35720417, 2022). "Although extensive and in-depth studies are needed to test the therapeutic benefits of targeting co-inhibitory pathways, current understanding indicates that enforcement of TIGIT axis may offer a new therapeutic approach for the treatment of autoimmune diseases." (PMID 35720417, 2022). "describe TIGIT expression on a small percentage of monocytes in healthy individuals and showed that there might be a tendency for a higher percentage of TIGIT expressing monocytes in autoimmune diseases such as rheumatoid arthritis and systemic lupus erythematosus." (PMID 34276685, 2021). "Together, these data suggest that the TIGIT+KLRG1+ CD8+ T cell population is primarily composed of TEX and is present in the peripheral blood in healthy individuals, individuals with autoimmune disease, and cancer." (PMID 38650930, 2024). "The PVR/TIGIT/CD226/CD96 signalling axis represents a promising therapeutic target for both cancer immunotherapy and the treatment of autoimmune diseases." (PMID 36944702, 2023). "Dermatomyositis (DM) is an autoimmune disease, in which T cell dysregulation plays a pivotal role, and importantly, it is a common immune-related adverse event in response to treatment of cancers with immune checkpoint inhibitors, but no studies have implicated the TIGIT/CD226 axis in DM." (PMID 33413573, 2021). "However, the role of the TIGIT/CD226 axis in autoimmune diseases remains unclear." (PMID 33413573, 2021). "Considering that Treg and dendritic cells are involved in the pathogenesis of autoimmune disease, exploring the balance of the CD226/TIGIT immune checkpoint in these cells is also needed for a deeper understanding of PBC." (PMID 32793241, 2020).